ZBTB10 (zinc finger and BTB domain containing 10)
Description:
May be involved in transcriptional regulation.
Synonyms: RINZF; FLJ12752
Tractability: PROTAC: UniProt records ubiquitination sites on it; ubiquitination databases record sites on it.
Target class: Transcription factor
Gene: Protein-coding gene on chromosome 8 (80,485,596 to 80,526,265, forward strand). Ensembl gene ENSG00000205189.
Subcellular location: Nucleus
Subcellular location (Human Protein Atlas): Nucleoplasm
Gene Ontology:
Molecular function: protein binding; telomeric DNA binding; DNA-binding transcription repressor activity, RNA polymerase II-specific; RNA polymerase II transcription regulatory region sequence-specific DNA binding
Biological process: negative regulation of transcription by RNA polymerase II
Cellular component: chromosome, telomeric region; nucleoplasm; nucleus
Genetic constraint (gnomAD): Loss-of-function variants: 32 observed, 68.66 expected, observed/expected ratio (o/e) 0.47, 90% interval 0.35 to 0.63. The synonymous counts are far from expectation, so gnomAD's model fits this gene poorly and the ratio says little. Missense variants: 1,057 observed, 1,045.5 expected, observed/expected ratio (o/e) 1.01, 90% interval 0.96 to 1.06. Synonymous variants: 523 observed, 411.28 expected, observed/expected ratio (o/e) 1.27, 90% interval 1.18 to 1.37.
Homologues: Orthologues: chimpanzee ZBTB10 (99% identical), macaque ZBTB10 (99% identical), dog ZBTB10 (96% identical), rabbit ZBTB10 (96% identical), pig ZBTB10 (94% identical), rat Zbtb10 (88% identical), mouse Zbtb10 (88% identical), guinea pig ZBTB10 (77% identical), tropical clawed frog zbtb10 (50% identical), zebrafish zbtb10 (37% identical). Paralogues in human: ZBTB8B (16% identical), ZBTB8A (16% identical), ZBTB22 (12% identical), ZBTB9 (10% identical), C17orf113 (7% identical).
Diseases named in the same sentence as ZBTB10 in open-access papers:
ZBTB10 is named in the same sentence as 24 diseases in open-access papers, as found by Europe PMC text mining. Sharing a sentence is not in itself a finding about the gene and the disease. The quoted sentences say what the papers report.
breast cancer (14 papers, 2012 to 2025). A primary or metastatic malignant neoplasm involving the breast. "The univariate analyses indicated that miR-27a expression, as well as T-stage, N-stage and ZBTB10 expression, was significantly associated with disease-free survival (P = 0.001) of breast cancer patients." (PMID 23240057, 2012). "To further evaluate whether miR-27a high-expression was linked to the clinical progression of breast cancer, we analyzed the association of miR-27a and ZBTB10 expression with the clinicopathological status of breast cancer patients." (PMID 23240057, 2012). "According to the findings from our previous work, the risk of developing breast cancer was influenced by rs10454142 PPP1R21, while the likelihood of developing endometriosis was determined by rs440837 [A/G] ZBTB10." (PMID 40724651, 2025). "According to the previously obtained data, susceptibility to breast cancer is determined by the rs10454142 PPP1R21, and predisposition to endometriosis was determined by the rs440837 ZBTB10." (PMID 41010401, 2025). "A second study reported that treatment of breast cancer cells with an HDAC inhibitor induced expression of an Sp repressor gene ZBTB10 and this was accompanied by downregulation of miR-27b, which is part of the miRNA-23a-27a-24-2 cluster." (PMID 36982239, 2023). "Univariate and multivariate analysis showed that both miR-27a and ZBTB10 were independent prognostic factors of disease-free survival in breast cancer patients (p < 0.001), while only miR-27a was an independent predictor of the overall survival (p < 0.001)." (PMID 35740618, 2022). "We consulted the Human Protein Atlas Interactive Analysis to validate the expression of the core driver genes, including IDI1, BNIP3, IFRD1, COQ10B, and ZBTB10, at the protein and RNA levels in breast cancer." (PMID 34226298, 2021). "On the contrary, it was reported that miR-27a indirectly regulates estrogen receptorα expression and hormone responsiveness in MCF-7 breast cancer cells through the suppression of ZBTB10." (PMID 23240057, 2012). "The expression of miR-27a and ZBTB10 was examined in 102 breast cancer cases using in situ hybridization (ISH) and immunohistochemistry techniques and were evaluated semi-quantitatively by examining the staining index." (PMID 23240057, 2012). "A reverse correlation between miR-27a and ZBTB10 was also observed in breast cancer tissue samples (rs = −0.478, P<0.001)." (PMID 23240057, 2012). "Clinicopathological Characteristics of the Patients and the Expression of miR-27a and ZBTB10 in breast cancer." (PMID 23240057, 2012). "Univariate and multivariate analysis showed that both miR-27a and ZBTB10 were independent prognostic factors of disease-free survival in breast cancer patients (P <0.001), while only miR-27a was an independent predictor of overall survival (P <0.001)." (PMID 23240057, 2012). "On the contrary, ZBTB10 expression was negatively correlated with tumor size, lymph node metastasis and the distant metastasis of breast cancers." (PMID 23240057, 2012). "Research has shown that ZBTB10 inhibits breast cancer metastasis." (PMID 40490947, 2025). "By binding to the miRNA promoter, RUNX1 increases the transcriptional level of miR-27a in breast cancer and concomitantly the decreases expression of ZBTB10, a direct target gene of miR-27a, to promote endothelial differentiation and subsequent angiogenesis and tumor metastasis." (PMID 32102656, 2020). "In addition, Spearman order correlation analysis showed that ZBTB10 expression in breast cancer was inversely correlated with the miR-27a level." (PMID 23240057, 2012). "Previous studies have demonstrated that ZBTB10/RINZF is a direct target of oncogenic miR-27a in breast cancers and colon cancer cell lines, but this could not be the case in the colorectal cancer tissues because herein miR-27a seemed to be a tumor suppressor in colorectal cancers." (PMID 25166914, 2014).
breast cancer (continued). "In particular, Zinc Finger and BTB Domain Containing 10 (ZBTB10, also known as RINZF) is known to be down-regulated by miR-27a in breast cancer cells, particularly MDA-MB-231 cells." (PMID 35110406, 2022). "Like miR-27a, the difference in the expression of ZBTB10 between metastatic and non-metastatic breast cancers was statistically significant." (PMID 23240057, 2012). "However, the level of ZBTB10 expression was lower in breast cancers patients with distant metastasis,compared with non-metastatic cancers." (PMID 23240057, 2012).
colon cancer (6 papers, 2011 to 2022). "Another paper suggested that ROS induced by curcumin can reverse drug resistance phenotypes in colon cancer cells by the suppression of microRNA-27a and induction of ZBTB10." (PMID 36499286, 2022). "The similar observation presented in Noratto's study and the role of microRNA 27a was played through microRNA-27a-ZBTB10-Sp axis in colon cancer." (PMID 29100439, 2017). "Sulindac sulfide also induced reactive oxygen species (ROS) and decreased the level of microRNA-27a in colon cancer cells, which resulted in the upregulation of the Sp-repressor ZBTB10 and this resulted in downregulation of Sp proteins." (PMID 26673922, 2015). "Chintharlapalli and colleagues demonstrated, for the first time, that CDODA-Me, a synthetic derivative of glycyrrhetinic acid, acts by downregulating miR-27a that is accompanied by an enhanced expression of ZBTB10 and Myt-1 which produces cell cycle arrest in colon cancer cells." (PMID 25915942, 2015). "Since overexpression of ZBTB10 and antisense-miR-27a also decreases expression of Sp1, Sp3, Sp4 and Sp-regulated genes in colon cancer cells, the mechanism of action of BA in RKO cells is linked to disruption of miR-27a:ZBTB10 as previously reported for CDODA-Me and GT-094 in colon cancer cells." (PMID 21864401, 2011). "Moreover, in colon cancer cells where curcumin induces reactive oxygen species (ROS), curcumin was found to down-regulate microRNAs miR-27a, miR-20a, and miR-17-5p and regulate transcriptional repressors ZBTB10 and ZBTB4." (PMID 36499286, 2022).
asthma (5 papers, 2021 to 2026). "It has been argued that ZBTB10's repression of the Sp1 transcription factor, which regulates a number of cytokine-related genes, may account for the association of this gene with asthma." (PMID 39241920, 2024). "For example, SNPs of ZBTB10 affect the asthma risk through the cis-regulation of its genes." (PMID 35967302, 2022). "We link discovered eQTLs to associations identified in pediatric and adult asthma and atopy traits, nominating 78 eGenes like TRAF3, ZBTB10 and JAZF1 in disease relevant cell types." (PMID 41889912, 2026). "rs12543811 is located between genes TPD52 and ZBTB10 and has moderate H3K27ac fold change values in asthma relevant cell types (mean percentile is 52th)." (PMID 34669738, 2021). "An example would be rs116716490 which is part of the ZBTB10 gene, previously associated with asthma via GWAS78, but not selected by LASSO." (PMID 37468507, 2023).
endometriosis (4 papers, 2024 to 2025). The growth of functional endometrial tissue in anatomic sites outside the uterine body. "Well, we found that SHBG-raising genotype GG rs440837 (A > G) ZBTB10 causes an almost twofold increase in the endometriosis risk (OR = 1.91)." (PMID 41373783, 2025). "At the same time, two genetic markers—rs440837 (A > G) ZBTB10 (it is an independent risk factor for endometriosis) and rs3779195 (T > A) BAIAP2L1, have been involved in the formation of the largest number of SNP-SNPinter models—4 and 3 models, respectively." (PMID 41373783, 2025). "Interestingly enough, according to our in silico data, rs7013042, strongly linked to the endometriosis-causal SNP rs440837 (A > G) ZBTB10, affects the “DNA-Sp4” interaction." (PMID 41373783, 2025). "Importantly, endometriosis-causal SNP rs440837 (A > G) ZBTB10 itself and the strongly linked variant rs7013042 manifest functional activity in the liver, which is the organ of SHBG formation." (PMID 41373783, 2025). "There were 12 molecules that returned no search results on PubMed, including the transcription regulators IRF2BP2, TBX2 and ZBTB10, suggesting that these endogenous molecules could have as yet unidentified roles in the establishment of endometriosis lesions." (PMID 39385609, 2024). "Given the established role of ZBTB10 in malignancy and its impact on angiogenesis, defining its involvement in endometriosis could offer crucial insights into disease mechanisms and potentially inform new therapeutic approaches." (PMID 39385609, 2024). "Endometriosis-associated SNP-SNPinter models include 7 SNPs from 9 analyzed loci, such as rs17496332 (A > G) PRMT6, rs780093 (C > T) GCKR, rs10454142 (T > C) PPP1R21, rs3779195 (T > A) BAIAP2L1, rs440837 (A > G) ZBTB10, rs7910927 (G > T) JMJD1C, and rs8023580 (T > C) NR2F2." (PMID 41373783, 2025). "This may be one of the pathophysiological mechanisms of the rs440837 (A > G) ZBTB10 (with rs7013042) communicating with the SHBG level and their involvement in endometriosis pathogenesis due to this." (PMID 41373783, 2025).
gastric cancer (2 papers, 2013 to 2025). A primary or metastatic malignant neoplasm involving the stomach. "Moreover, the rs895819 variant was an important factor of gastric cancer predisposition by regulating miRNA‐27a and ZBTB10 levels." (PMID 39840720, 2025).
invasive breast carcinoma (2 papers, 2012 to 2023). A carcinoma that infiltrates the breast parenchyma. "miR-27a was markedly up-regulated in invasive breast cancers that expressed low levels of ZBTB10 (P<0.001)." (PMID 23240057, 2012). "In addition, Spearman order correlation analysis showed that ZBTB10 expression in invasive breast cancer was inversely correlated with the miR-27a level (rs = −0.478, P<0.001)." (PMID 23240057, 2012).
ovarian carcinoma (2 papers, 2024 to 2025). A malignant neoplasm originating from the surface ovarian epithelium. "There are literature data on the association of the ZBTB10 gene with SHBG- and sex hormone-dependent tumors such as breast and ovarian cancers." (PMID 41373783, 2025). "Overexpression of ZBTB10 in human ovarian cancer cell lines led to suppression of FSH-induced angiogenesis by downregulating VEGF, COX2 and survivin [baculoviral inhibitor of apoptosis repeat-containing 5 (BIRC5)]." (PMID 39385609, 2024).
pancreatic cancer (2 papers, 2023 to 2025). "On the other hand, miR-27a levels decreased upon metformin treatment in pancreatic cancer cells, upregulating transcription factor repressors (zinc finger and BTB domain-containing protein 10 (ZBTB10)) of the specificity protein (Sp)." (PMID 38004379, 2023).
bladder cancer (1 paper, 2012). "Induction of ROS by CDDO-Me, BA/GT-094 and celastrol in pancreatic, colon and bladder cancer cells, respectively, results in downregulation of miR-27a and induction of ZBTB10." (PMID 23194063, 2012).
colonic adenocarcinomas (1 paper, 2021). "In contrast, ZBTB10 (Zinc Finger and BTB Domain-Containing Protein 10), which encodes for a zinc finger protein, has been found in isolated fusion events with other partner genes in breast and colonic adenocarcinomas." (PMID 34745213, 2021).
laryngeal carcinoma (1 paper, 2023). Carcinoma that arises from the laryngeal epithelium. "ZBTB10 was highly expressed in laryngeal cancer tissues and localized in both the nucleus and cytoplasm." (PMID 37834257, 2023). "To confirm that intermittent hypoxia induces the carcinogenic effect of M2 macrophages through ZBTB10, we further investigated the effect of M2 macrophage supernatant on ZBTB10 knockout laryngeal cancer cells." (PMID 37834257, 2023). "As ZBTB10-mediated regulation of HK1 affects glycolysis in laryngeal cancer, our findings may provide new potential therapeutic targets for laryngeal cancer." (PMID 37834257, 2023). "In addition, Pearson correlation analysis showed that the HK1 expression level was positively correlated with the ZBTB10 expression level in the laryngeal cancer tissue microarray (R2 = 0.3157; p < 0.0001)." (PMID 37834257, 2023). "This suggests that knocking out ZBTB10 could reverse the effect of culture supernatant from M2 macrophages exposed to IH on laryngeal cancer cells." (PMID 37834257, 2023). "We next confirmed that the expression trend was consistent between ZBTB10 and HK1 in human laryngeal cancer tissues." (PMID 37834257, 2023). "Knockdown of ZBTB10 decreased HK1 expression, and overexpression of ZBTB10 increased HK1 expression in both laryngeal cancer cells and 293T cells." (PMID 37834257, 2023). "By constructing ZBTB10-sgRNA and knocking out ZBTB10 in Hep2 cells, we found that, after the knockout, both the mRNA and protein levels of HK1 were decreased in laryngeal cancer Hep2 cells." (PMID 37834257, 2023). "IH promotes TAM-induced glycolysis in laryngeal cancer cells via regulation of HK1 expression through activation of CLEC3B and ZBTB10." (PMID 37834257, 2023). "We performed immunohistochemical staining of a tissue microarray containing 80 samples of human laryngeal cancer tissue to determine the expression patterns of HK1 and ZBTB10." (PMID 37834257, 2023). "Comprehensive RNA-seq analysis disclosed a marked elevation in the expression levels of the transcription factor ZBTB10, while evaluation of a laryngeal cancer patient tissue microarray demonstrated a positive correlation between ZBTB10 and HK1 expression in laryngeal carcinoma." (PMID 37834257, 2023). "Hence, our results confirmed that ZBTB10 binds to a candidate sequence in the promoter of HK1 and transcriptionally regulates HK1 gene expression, increasing glycolysis and affecting malignant phenotypes in laryngeal cancer cells." (PMID 37834257, 2023). "Additionally, we demonstrate that HK1 is transcriptionally regulated by ZBTB10, indicating that targeting ZBTB10 or HK1 may be a potential approach for treating laryngeal cancer patients with OSA." (PMID 37834257, 2023).
lymph node metastasis (1 paper, 2012). "ZBTB10 levels were closely associated with tumor size, lymph node metastasis and distant metastasis of the patients." (PMID 23240057, 2012).
prostate tumors (1 paper, 2022). "The IHC analysis showed higher levels of PKLR in prostate tumors in patients who received ADT compared to the same patients before ADT; however, ZBTB10 levels were higher in patients before ADT and lower in patients after ADT." (PMID 35306527, 2022). "IHC results showed a reverse correlation between ZBTB10 and PKLR in consecutive tissue sections of prostate tumor samples." (PMID 35306527, 2022).
renal carcinoma (1 paper, 2022). A carcinoma arising from the epithelium of the renal parenchyma or the renal pelvis. "The combination of quercetin and hyperoside at a 1 : 1 ratio inhibits 786‐O renal cancer cell proliferation by upregulating the expression of zinc finger and BTB domain containing 10 (ZBTB10) and downregulating the mRNA expression of Sp1, Sp3, and Sp4." (PMID 35529922, 2022).
virus infection (1 paper, 2015). "In contrast, potential sumoylated forms of ZBTB4, ZBTB10 and ETV6 appeared to increase in abundance in the ICP0-null mutant infected samples, which may be related to the overall accumulation of sumoylated species that occurs during the mutant virus infection." (PMID 26200910, 2015).
tumor (16 papers, 2012 to 2025). "ZBTB10 binds directly to telomere repeat variants and may play a tumor suppressive role through inhibition of Sp transcription factors." (PMID 34445083, 2021). "We demonstrated that overexpression of ZBTB10 can suppress the glycolysis and oncogenic effects of PKLR, indicating the tumor-suppressive role of ZBTB10 in PCa." (PMID 35306527, 2022). "ZBTB10 is a transcriptional inhibitor of regulatory genes of the specific protein (SP) family of transcription factors, and was shown to play a tumor-suppressive role in ovarian epithelial cancer cells." (PMID 35306527, 2022). "The oncogenic effect of miR-27a can be mediated through the regulation of the target ZBTB10 (zinc finger and BTB domain containing 10) gene known to be involved in tumor growth, metastasis and chemotherapy resistance." (PMID 29100393, 2017). "Abnormal interaction between ZBTB10 and Sp1 is seen in several different cancer cell lines, with ZBTB10 consistently exhibiting tumour-suppressing activity." (PMID 27539887, 2016). "MicroRNA-27a (miR-27a) is thought to be an onco-microRNA that promotes tumor growth and metastasis by downregulating ZBTB10." (PMID 23240057, 2012). "Among these upregulated genes, Dennd4a, Nfil3, Hspa1b, Chac1, Ddit4, Mex3b, Lysmd3, and Zbtb10 are mainly involved in oxidative stress and inflammation response, whereas Plcxd2, Dusp1, Cep85l, and Dusp8 are generally considered as tumor‐suppressor genes by inhibiting proliferation of cancer cells." (PMID 40231790, 2025). "Furthermore, it is also involved in the regulation of the ZBTB10 gene, which is related to up-regulating Sps proteins important to tumor survival and angiogenesis." (PMID 37445965, 2023). "ZBTB10 can be down-regulated by MicroRNA-27a (miR-27a) to promote tumor growth and metastasis." (PMID 36407095, 2022). "Furthermore, the expression of miR-27a and ZBTB10 was significantly correlated with clinicopathological parameters, including tumor size, lymph node metastasis and distant metastasis (P<0.05), but not with receptor status." (PMID 23240057, 2012). "This may contribute to the ZBTB10 regulation of Sp, which is related to tumor growth and metastasis." (PMID 23240057, 2012). "MiR-27a, as well as ZBTB10, was expressed in the cytoplasm of most neoplastic tumor cells." (PMID 23240057, 2012). "An additional upstream regulator, zinc finger and BTB domain-containing 10 (ZBTB10), affects cell cycle regulation, apoptosis and tumor angiogenesis." (PMID 39385609, 2024). "ZBTB10 serves as a transcriptional inhibitor of SP1 transcription factors and participates in inhibiting tumor activities, including tumor growth, chemoresistance, and migration/invasion, suggesting that ZBTB10 should be considered a tumor suppressor." (PMID 35306527, 2022).